BCAM (basal cell adhesion molecule (Lutheran blood group))
Description:
Transmembrane glycoprotein that functions as both a receptor and an adhesion molecule playing a crucial role in cell adhesion, motility, migration and invasion. Extracellular domain enables binding to extracellular matrix proteins, such as laminin, integrin and other ligands while its intracellular domain interacts with cytoskeletal proteins like hemoglobin, facilitating cell signal transduction. Serves as a receptor for laminin alpha-5/LAMA5 to promote cell adhesion. Mechanistically, JAK2 induces BCAM phosphorylation and activates its adhesion to laminin by stimulating a Rap1/AKT signaling pathway in the absence of EPOR.
Synonyms: CD239; LU; MSK19; B-CAM; F8/G253; AU
Tractability: Antibody: UniProt places it where antibodies can reach, with high confidence; its Gene Ontology location is reachable by antibodies, with high confidence; UniProt predicts a signal peptide or a membrane-spanning region. PROTAC: ubiquitination databases record sites on it; its protein half-life has been measured.
Gene: Protein-coding gene on chromosome 19 (44,809,070 to 44,821,421, forward strand). Ensembl gene ENSG00000187244.
Subcellular location: Cell membrane
Subcellular location (Human Protein Atlas): Nucleoli fibrillar center
Gene Ontology:
Molecular function: laminin binding; laminin receptor activity; protein binding; transmembrane signaling receptor activity
Biological process: cell adhesion; cell-matrix adhesion; angiogenesis; signal transduction
Cellular component: extracellular exosome; extracellular matrix; extracellular region; plasma membrane; external side of plasma membrane; cell surface
Genetic constraint (gnomAD): Loss-of-function variants: 61 observed, 68.52 expected, observed/expected ratio (o/e) 0.89, 90% interval 0.72 to 1.1. The upper end of that interval is the gene's LOEUF score, 1.1, which puts it in group 4 of 6, group 1 being the genes least tolerant of losing a copy. Missense variants: 909 observed, 865.25 expected, observed/expected ratio (o/e) 1.05, 90% interval 0.99 to 1.11. Synonymous variants: 408 observed, 374.57 expected, observed/expected ratio (o/e) 1.09, 90% interval 1 to 1.18.
Homologues: Orthologues: chimpanzee BCAM (99% identical), macaque BCAM (96% identical), pig BCAM (81% identical), dog BCAM (74% identical), rat Bcam (73% identical), mouse Bcam (73% identical), guinea pig BCAM (72% identical), tropical clawed frog bcam (34% identical), zebrafish bcam (28% identical). Paralogues in human: MCAM (28% identical), ALCAM (22% identical), AGER (14% identical).
Diseases named in the same sentence as BCAM in open-access papers:
BCAM is named in the same sentence as 59 diseases in open-access papers, as found by Europe PMC text mining. Sharing a sentence is not in itself a finding about the gene and the disease. The quoted sentences say what the papers report.
ovarian carcinoma (9 papers, 2013 to 2025). A malignant neoplasm originating from the surface ovarian epithelium. "High expression of basal cell adhesion molecule (BCAM) is a hallmark of ovarian cancer (OC) progression." (PMID 40082910, 2025). "Prognostic value of BCAM expression for ovarian cancer was tested in association with survival outcomes of the cohorts." (PMID 39207605, 2024). "In ovarian carcinoma (OC), all BCAM forms are abundant and associated with poor survival, yet BCAM's contribution to peritoneal metastatic spread remains enigmatic." (PMID 36647260, 2023). "Expression of BCAM is associated with a poor survival of ovarian cancer." (PMID 36647260, 2023). "Ovarian carcinomas with varied histologic types showed prominent levels of BCAM expression in two ovarian tumor cohorts that were studied." (PMID 39207605, 2024). "Breast cancer patients demonstrated lower BCAM expression, compared to ovarian cancer and lung cancer (NSCLC)." (PMID 39207605, 2024). "Basal cell adhesion molecule (BCAM) is another important protein reported in ovarian cancer playing a key role in the metastasis process and immune suppression." (PMID 38918474, 2024). "Overexpression of BCAM is observed in many epithelial cell cancers, such as ovarian carcinoma, skin cancer, breast cancer, colorectal cancer, and hepatocellular carcinoma." (PMID 39207605, 2024). "A majority of studies identified the high expression of BCAM among malignancies, including epithelial skin tumor, ovarian cancer, bladder cancer and gastric cancer." (PMID 35941663, 2022). "In addition, BCAM overexpression has previously been described in epithelial skin tumors, ovarian cancer, pancreatic cancer, and hepatocellular carcinoma." (PMID 24223164, 2013). "In this study, we confidently identified the marker combination of EEF1G + MSLN + BCAM + TAGLN2 which showed upregulation in both serum and tissue an outperforming marker panel against currently available markers for ovarian cancer." (PMID 38918474, 2024). "In our study, we observed that ovarian carcinoma cases had high levels of BCAM expression, which did not correlate with PD-L1 expression since PD-L1 generally tends to be expressed at very low levels in this cancer type." (PMID 39207605, 2024).
bladder cancers (6 papers, 2017 to 2025). "It has also been reported that high levels of BCAM in renal, pelvic, ureteral, and bladder cancers are significantly associated with advanced tumor stage, larger tumor size, and lower disease-specific survival." (PMID 39207605, 2024). "The mutant form H-rasV12 can transcriptionally upregulate the expression of Lu/BCAM in bladder cancer cells." (PMID 39000374, 2024). "BCAM expression has been studied in several cancer types including ovarian, skin, lung, gastric, liver, thyroid, breast, and bladder cancer." (PMID 39207605, 2024). "Membranous expression of Lu/BCAM was observed in the basal compartment of the primary bladder cancer (arrow) as well as in the endothelium and smooth muscle cells of lamina propria (arrowhead)." (PMID 28841878, 2017). "We further disclosed that overexpression of Lu/BCAM suppressed endogenous Ras expression in a dosage dependent manner in T24 bladder cancer cells, indicating the existence of a feedback regulation." (PMID 28841878, 2017). "Lu/BCAM expression is dysregulated in various types of cancer, such as skin, breast, lung, and bladder cancers, and could act as a biomarker and target for the treatment of these diseases." (PMID 40332051, 2025). "Lu/BCAM expression was detected on the membrane of primary human bladder cancer cells." (PMID 28841878, 2017). "On the one hand, BCAM inhibits the adhesion of single OC cells to LN‐511 (presumably by competing for integrin binding), which may have an inhibitory impact on metastasis, consistent with studies of gastrointestinal and bladder carcinoma cells." (PMID 36647260, 2023). "We showed that laminin stimulates Lu/BCAM to increase the adhesion of NIH-Lu and bladder cancer cells through RhoA/Rac1 signalling pathway." (PMID 28841878, 2017). "BCAM was not prognostic for OS in bladder cancer patients with available clinical information, (p = 0.215; HR = 0.795 for median cut point) and (p = 0.891; HR = 0.971 for visual cut point)." (PMID 39207605, 2024).
breast carcinoma (6 papers, 2018 to 2024). "The expression of BCAM in breast cancer patients indicates that it is a promising target for therapies such as antibody–drug conjugates (ADCs)." (PMID 39207605, 2024). "Additionally, Lu/BCAM is upregulated in the blood of patients with pancreatic and breast cancer." (PMID 39000374, 2024). "Despite these challenges, we noted a broad range of BCAM expression in various tumor types, including ovarian, lung (NSCLC), HNSCC, bladder, and breast cancers, highlighting its potential as a therapeutic target." (PMID 39207605, 2024). "BCAM expression was not prognostic for OS in breast cancer patients either using median cut point (p = 0.571; HR = 0.811) or visual cut point (p = 0.158; HR = 0.709)." (PMID 39207605, 2024).
colon carcinoma (6 papers, 2017 to 2024). "In this context, it is noteworthy that KRAS‐mutated colon carcinoma cells express high levels of BCAM and efficiently form hepatic metastases in mice, which is inhibited by BCAM‐mimetic peptides blocking LAMA5–BCAM interaction." (PMID 36647260, 2023). "The low expression of BCAM has only been found in thyroid cancer and colon cancer." (PMID 35941663, 2022). "Of particular interest in the context of our findings may be the observation that BCAM and laminin-55 have been reported to mediate the interaction of tumor cells and the endothelium to promote the metastatic spreading of colon cancer cells." (PMID 31588238, 2019). "It has been found that inhibition of BCAM impairs KRAS-mutant colon cancer cells’ specific adhesion to endothelial cells, but not to pericytes, but the mechanism is not known." (PMID 39835116, 2024).
colorectal cancer (6 papers, 2019 to 2025). A primary or metastatic malignant neoplasm that affects the colon or rectum. "Inhibiting either BCAM or laminin α5 can disturb the adhesion between colorectal cancer cells harboring KRAS mutations and endothelial cells." (PMID 39000374, 2024). "Recent studies have shown that Lu/BCAM is involved in regulating the adhesion between KRAS-mutated colorectal cancer cells and endothelial cells." (PMID 39000374, 2024). "Therefore, BCAM/laminin α5 may exert a significant role in the metastatic process of colorectal cancer cells with KRAS mutations." (PMID 39000374, 2024). "Abnormal expression of Lu/BCAM is closely associated with the occurrence and progression of various diseases, including sickle cell anemia (SCA), liver cancer, lung cancer, colorectal cancer, bladder cancer, etc.." (PMID 39000374, 2024). "BCAM is highly expressed in KRAS-mutant hepatic metastases from colorectal cancer, and inhibition of BCAM/LAMA5 interferes with the adhesion of colorectal cells to vascular endothelial cells, thereby reducing metastatic growth." (PMID 36672394, 2023). "Inhibition of BCAM impaired adhesion of KRAS‐mutant colorectal cancer cells specifically to endothelial cells." (PMID 31951095, 2020). "The previous study has shown that BCAM plays a functional role in the metastatic spreading of KRAS‐mutant colorectal cancer." (PMID 31951095, 2020). "Emerging studies have shown that BCAM plays an important role in tumor progression, including skin tumors, hepatocellular carcinoma, colorectal cancer, and bladder cancer." (PMID 31951095, 2020). "In colorectal cancer, Lu/BCAM is overexpressed in clinical KRAS-mutant hepatic metastasis and the inhibition of its interaction with laminin α5 impaired adhesion of colorectal cancer cells to vascular endothelial cells, resulting in a reduction of metastatic growth." (PMID 40332051, 2025). "BCAM was reported to mediate recognition between tumor cells and the endothelium in KRAS-Mutant colorectal cancer." (PMID 32063918, 2019).
lung carcinoma (6 papers, 2015 to 2024). "In lung cancer (NSCLC), 78.5% of the population (n = 281/545 cases) showed visible BCAM expression signal (positive cases)." (PMID 39207605, 2024).
sickle cell anemia (6 papers, 2019 to 2025). "Particularly, Lu/BCAM mediates abnormal red blood cell adhesion to laminin in sickle cell disease and hereditary spherocytosis, due to the phosphorylation of the long isoform cytoplasmic domain or by its dissociation from the spectrin-based skeleton." (PMID 40332051, 2025). "Vascular obstructions, a major acute complication of sickle cell disease, occur due to abnormal adhesion between blood cells and endothelial cells in the microcirculation, which involves integrin α4β1 and its interaction with Lu/BCAM in endothelial cells." (PMID 39000374, 2024). "Notably, the blood group antigen Lu/BCAM is also involved in other diseases including sickle cell disease." (PMID 30841639, 2019). "BCAM1 has also been shown to be phosphorylated by glycogen synthase kinase 3β, casein kinase II and PKA at serines 596, 598 and 621, respectively and the phosphorylation state of BCAM might be a critical factor for adhesion of erythrocytes to LAMA5 in sickle cell anemia." (PMID 36647260, 2023). "Abnormal adhesion of RBCs was first observed in sickle cell anemia involving vascular cell adhesion molecule (VCAM)-1, α4β1, Lu/BCAM, and intercellular adhesion molecule (ICAM)-4." (PMID 32727002, 2020).
delirium (5 papers, 2021 to 2026). A disorder characterized by confusion; inattentiveness; disorientation; illusions; hallucinations; agitation; and in some instances autonomic nervous system overactivity. "Delirium prevalence (positive bCAM) at enrollment was 47.0% (95% CI, 43.5%-50.5%) in the primary cohort versus 43.6% in the 7-day point prevalence study." (PMID 33571227, 2021). "The use of the bCAM in this study may further strengthen its results because of its modest sensitivity (78%) and high specificity (97%) which would bias towards the null and under-estimate delirium." (PMID 36755624, 2023). "Patients were classified as having normal cognition (bCAM negative, 10-CS > 5), delirium (bCAM positive), or cognitive impairment without delirium (bCAM negative, 10-CS ≤ 5)." (PMID 41958224, 2026).
polycythemia vera (5 papers, 2019 to 2025). "In polycythemia vera the muted JAK2 kinase causes phosphorylation of BCAM (CD239) which is a receptor for endothelial laminin-α5, and this may well be a main source of RBC adhesiveness." (PMID 37373527, 2023). "In polycythemia vera, red blood cells have abnormal expression of Lu/BCAM and hydroxycarbamide enhances Lu/BCAM phosphorylation and exacerbates cell adhesion to laminin." (PMID 40332051, 2025). "It has been shown that adherence increases in such patients; in particular, in polycythemia vera, there is an overexpression of Lu/BCAM, two glycoprotein isoforms of the immunoglobulin superfamily that represent the receptors for the α5 chain of laminin." (PMID 38673505, 2024).
epithelial skin tumor (4 papers, 2013 to 2022). "The distribution of Lu/BCAM protein around plasma membrane of bladder cancer cells and at basal compartment of bladder cancer tissue is consistent with finding of Lu/BCAM in epithelial skin tumor." (PMID 28841878, 2017). "BCAM is induced in epithelial skin tumors, and haptotactic migration of BCAM overexpressing NIH3T3 cells is significantly increased on the laminin matrix." (PMID 24223164, 2013). "Furthermore, Lu/BCAM is highly expressed in epithelial skin tumors as well as in hepatic metastasis from colorectal cancer." (PMID 29267242, 2017).
gastric cancer (4 papers, 2020 to 2024). A primary or metastatic malignant neoplasm involving the stomach. "Elevated levels of BCAM were observed in gastric cancer (GC) tissues with metastasis, compared to those in tissues without metastasis." (PMID 39000374, 2024). "BCAM is differentially expressed in some tumors: highly expressed in tumors like epithelial skin, ovarian, bladder and gastric cancer and downregulated in some other types of malignancies." (PMID 35941663, 2022). "Unfortunately, only one study tried to explore the probable regulation of BCAM in gastric cancer." (PMID 35941663, 2022). "BCAM, involved in cell adhesion and migration, can also promote tumor metastasis and has been elucidated to play a functional role in the metastasis of thyroid cancer and gastric cancer." (PMID 35941663, 2022). "Few studies focus on the regulatory mechanism of abnormal expression of BCAM in tumors, except one reported that BCAM expression was modulated by lncRNA BAN in gastric cancer." (PMID 35941663, 2022). "We found that the levels of BCAM and its sense lncRNA BAN were increased in gastric cancer (GC) tissues with metastasis." (PMID 31951095, 2020).
hepatoma (4 papers, 2013 to 2024). "Studies have revealed that silencing FBI1/Akirin2 expression in rat hepatoma K2 cells leads to a significant upregulation of Lu/BCAM mRNA expression." (PMID 39000374, 2024). "To elucidate the detailed function of BCAM in malignant tumors, we established BCAM-expressing hepatoma K2 cells." (PMID 24223164, 2013). "Our results suggest that BCAM functions as a tumor suppressor in rat hepatocellular carcinoma K2 cells." (PMID 24223164, 2013). "Furthermore, co-expression of Lu/BCAM and integrin on the cell surface is responsible for adhesion of hepatocellular carcinoma cells." (PMID 28841878, 2017).
pancreatic cancer (4 papers, 2013 to 2024). "Little is known about the role of BCAM in pancreatic cancer, but laminin alpha 5 is widely expressed in basement membranes, and therefore it has been suggested that BCAM may play a role during the process of tumor invasion." (PMID 24708694, 2014). "Similarly, BCAM was not expressed (0.8%, n = 2/223) in the pancreatic cancer cases (YTMA-454)." (PMID 39207605, 2024).
squamous cell carcinoma (4 papers, 2022 to 2024). A carcinoma arising from squamous epithelial cells. "In skin tumor tissues, such as basal cell carcinoma, squamous cell carcinoma and keratoacanthoma, BCAM is upregulated compared to normal skin tissue." (PMID 39000374, 2024). "Niiya and colleagues identified BCAM as a substrate of MMP14 in human epidermoid carcinoma A431 cells to produce a cleavage product of unknown function." (PMID 36647260, 2023). "Moreover, BCAM is overexpressed in both basal cell and squamous cell carcinomas compared with normal skin cells, suggesting that a potential role for BCAM in these cancers warrants further investigation." (PMID 35969606, 2022). "The higher levels of BCAM protein expression were seen in ovarian, lung (NSCLC), breast, bladder, pancreatic and squamous cell carcinoma tissues." (PMID 39207605, 2024).
liver cancer (3 papers, 2018 to 2024). An epithelial or non-epithelial malignant neoplasm that arises from the liver. "Silencing FBI1/Akirin2 expression leads to increased Lu/BCAM expression, while the overexpression of Lu/BCAM inhibits crucial biological behaviors, such as clone formation, cell migration and invasion in rat liver cancer cells." (PMID 39000374, 2024). "FBI1/Akirin2, a binding partner of 14-3-3β and typically associated with tumor promotion, has been found to target Lu/BCAM as a gene in rat liver cancer cells." (PMID 39000374, 2024). "To investigate the expression of Lu/BCAM (CD239) in human liver disease, we performed immunostaining of CD239 for a few resected samples obtained from the surgery to remove liver cancer." (PMID 30059007, 2018). "Lu/BCAM is found to be upregulated in liver cancer tissues, including poorly and well-differentiated tumors, and interacts with integrin α6β1 to competitively bind laminin, modulating the adhesion capacity of liver cancer cells." (PMID 39000374, 2024).
glioma (2 papers, 2013 to 2025). A benign or malignant brain and spinal cord tumor that arises from glial cells (astrocytes, oligodendrocytes, ependymal cells). "Another transmembrane receptor, BCAM (CD239), exhibits significantly increased expression in glioblastomas compared to normal brain tissue and low-grade gliomas, constituting an unfavorable prognostic factor." (PMID 41304780, 2025). "In addition, FBI1/Akirin2 suppressed the BCAM promoter activity in a variety of cell lines such as rat glioma C6, Huh7, HeLa and COS-7, by luciferase reporter assay." (PMID 24223164, 2013).
thrombosis (2 papers, 2018 to 2019). "This thrombosis risk appears to be mediated in part by viscosity from increased haematocrit, in part by increased binding to endothelial laminin as a result of an JAK2 V617F driven activation of Lu/BCAM and from increased neutrophil extracellular trap formation." (PMID 30558676, 2018).
Alzheimer disease (1 paper, 2020). A progressive, neurodegenerative disease characterized by loss of function and death of nerve cells in several areas of the brain leading to loss of cognitive function such as memory and language.